ZSCAN25 (zinc finger and SCAN domain containing 25)
Description:
May be involved in transcriptional regulation.
Synonyms: ZNF498; FLJ32468
Tractability: PROTAC: UniProt records ubiquitination sites on it; ubiquitination databases record sites on it.
Gene: Protein-coding gene on chromosome 7 (99,616,623 to 99,632,408, forward strand). Ensembl gene ENSG00000197037.
Subcellular location: Nucleus
Subcellular location (Human Protein Atlas): Nucleoli fibrillar center; Nucleoplasm
Pathways (Reactome):
Gene expression (Transcription): Generic Transcription Pathway
Gene Ontology:
Molecular function: DNA-binding transcription factor activity, RNA polymerase II-specific; RNA polymerase II cis-regulatory region sequence-specific DNA binding; sequence-specific DNA binding
Biological process: regulation of transcription by RNA polymerase II; regulation of DNA-templated transcription
Cellular component: nucleus
Genetic constraint (gnomAD): Loss-of-function variants: 35 observed, 48.17 expected, observed/expected ratio (o/e) 0.73, 90% interval 0.55 to 0.96. The upper end of that interval is the gene's LOEUF score, 0.96, which puts it in group 4 of 6, group 1 being the genes least tolerant of losing a copy. Missense variants: 637 observed, 713.57 expected, observed/expected ratio (o/e) 0.89, 90% interval 0.84 to 0.95. Synonymous variants: 273 observed, 277.38 expected, observed/expected ratio (o/e) 0.98, 90% interval 0.89 to 1.09.
Homologues: Orthologues: chimpanzee ZSCAN25 (99% identical), macaque ZSCAN25 (97% identical), dog ZSCAN25 (90% identical), rabbit ZSCAN25 (87% identical), pig ZSCAN25 (87% identical), guinea pig ZSCAN25 (85% identical), mouse Zscan25 (84% identical), rat Zscan25 (83% identical). Paralogues in human: ZNF263 (37% identical), ZNF394 (34% identical), ZSCAN30 (33% identical), ZKSCAN8 (32% identical), ZKSCAN4 (32% identical), ZKSCAN3 (32% identical), ZSCAN21 (31% identical), ZSCAN22 (31% identical), ZNF397 (31% identical), ZSCAN12 (31% identical), ZNF449 (30% identical), ZKSCAN1 (30% identical), and 18 more.
Diseases named in the same sentence as ZSCAN25 in open-access papers:
ZSCAN25 is named in the same sentence as 6 diseases in open-access papers, as found by Europe PMC text mining. Sharing a sentence is not in itself a finding about the gene and the disease.
ZSCAN25 shares sentences with these, for which no sentence is quoted: hepatocellular carcinoma (2 papers); cancer (1); liver cancer (1); ovarian carcinoma (1); steatosis (1); tumor (1).